MERTK (MER proto-oncogene, tyrosine kinase)
Diseases named in the same sentence as MERTK in open-access papers (continued):
Sharing a sentence is not in itself a finding about the gene and the disease.
infection (26 papers, 2014 to 2026). The state of being infected such as from the introduction of a foreign agent such as serum, vaccine, antigenic substance or organism. "LN-resident macrophages possess immunoregulatory function that protect against pathogenic infection and inflammatory insults, and MerTk signalling in macrophages has been linked to anti-inflammatory outcomes." (PMID 39551813, 2024). "We observed that the infection of epithelial cultures resulted in elevated M-CSF that is known to upregulate PROS1 receptor MERTK on monocytes and macrophages." (PMID 40980495, 2025). "It has been shown that the treatment of a polyclonal anti-MERTK antibody (ab70693; Abcam, Cambridge, MA, USA) or homemade soluble MERTK ectodomain reduced the infection of classical swine fever virus and promoted the innate immune response." (PMID 33562150, 2021). "(G–L) Flow cytometry analysis of CD4 T cell (G), CD4/CD8 T cell ratio (H), γδ T cell (I), neutrophil (J), Ly6Chi cell (K), and CD64+ MerTK+ cell (L) on day 8 post (PFU 7e2) infection." (PMID 34151773, 2021). "Given the beneficial effect of MerTK on the potential enhancement of cardiac repair during infection, we consider MerTK to be a new, promising target to improve heart tissue repair and dampen cardiac dysfunction after infections in the elderly." (PMID 34342127, 2021). "Three weeks after infection, most lung macrophages (i.e., MerTK+CD64+) are AM accompanied by few IM." (PMID 32544188, 2020). "The results showed that the knockdown of MERTK dramatically decreased the intracellular viral genome replication and the progeny viruses in the supernatants at 48 h post-infection (hpi)." (PMID 32172658, 2020). "Additionally, we addressed whether MERTK is involved in the infection of genotype 2 CSFV-HLJ in PK-15 cells." (PMID 32172658, 2020). "Interestingly, the soluble MERTK ectodomain could also reduce the infection of bovine viral diarrhea virus (BVDV), another pestivirus." (PMID 32172658, 2020). "ANDV infection showed upregulation of cell type-specific viral entry genes (Calu-3: CD55 and ITGB3; hPSC-astrocytes: MERTK and VEGFA)." (PMID 40857262, 2025). "We compared the numbers of CD90.2+ T cells, Ly6G+ neutrophils, Ly6C+ inflammatory monocytes, MerTK+ CD64+ macrophages, and CD11c+ MHCII+ dendritic cells in naive and immune skin 72 hrs after infection." (PMID 28419151, 2017). "Over the course of infection, ExMФ upregulate the tissue macrophage-specific markers, CD169 and MerTK and also exhibit increased expression of macrophage-associated markers such as CD14 and F4/80." (PMID 26938654, 2016). "Besides their role during the course of infection with the intracellular parasite L. major, AXL and MERTK expression has been also detected during the inflammatory response induced by the helminth parasite Nippostrongylus brasiliensis (N. brasiliensis)." (PMID 34279684, 2021). "In Huh 7.0 cells, a TYRO3- and MERTK-positive cell line, EBOVΔVP30 infection induced the phosphorylation of TYRO3 in a HER2-dependent manner, but infection did not induce phosphorylation of MERTK." (PMID 33052961, 2020). "Frequencies of circulating CD163+CD16+ monocytes, regardless of MerTK expression, remained higher in rhesus macaques up until week 3 post-infection." (PMID 31736945, 2019). "Thus, to prevent the cardiac electrical dysfunction accompanied with aging that occurs during infections or endotoxin shock, we propose the use of an LXR activator, which leads to the increased expression of MerTK in the heart tissue and helps to maintain homeostasis and protect the heart." (PMID 34342127, 2021). "Considering our observation that JUNV modulates macrophage polarization and that AXL and MERTK are differentially expressed in pro-inflammatory M1 and anti-inflammatory M2 macrophages, respectively, we next evaluated TAM expression in HMDM after infection with both strains." (PMID 31695702, 2019).
infection (continued). "Similarly, the target genes of MERTK activation, the cytokine suppressors SOCS1 and SOCS3, were also increased after P strain infection, in addition to IRF-1, that regulates type I IFN levels, which were higher with C#1 compared with P strain infection." (PMID 31695702, 2019). "When assessing the ex vivo frequencies of CD163+ and MerTK+ double positive CD16+ monocytes we found that already at baseline rhesus macaques had significantly higher frequencies of MerTK+CD163+CD16+ monocytes, which were however markedly decreased from 3 weeks post-infection onward." (PMID 31736945, 2019). "PRV together with herpes simplex virus type 1 (HSV-1), of which infection is independent of TAM receptors, belong to the family Herpesviridae, indicating that MERTK is not required for PRV infection." (PMID 32172658, 2020). "LCMV-WE infection also induced expression of a non-conventional virus receptor, AXL-1, from the TAM (TYRO3/AXL/MERTK) family of receptor tyrosine kinases and this expression correlated with proliferation." (PMID 25822203, 2015).
retinopathy (7 papers, 2014 to 2025). "An intronic LINE-1 insertion in a putative regulatory region of the MERTK gene was found to be associated with a retinopathy in Swedish Vallhund dogs." (PMID 32894063, 2020). "We also screened the remainder of the genomic region spanning the MERTK gene (chr17:36,336,729–36,445,380) and found two additional intronic variants that were present in only the retinopathy case compared to the 49 other WGS." (PMID 28813472, 2017). "We have identified a LINE-1 insertion in intron 1 of the MERTK gene that is strongly associated with retinopathy in the Swedish Vallhund, and which is a strong candidate for a causative mutation." (PMID 28813472, 2017). "In conclusion, we have mapped the cause of retinopathy in SVs and show the involvement of the up-regulated MERTK gene in the affected dogs." (PMID 25517981, 2014). "Collectively, these results indicate that the retinopathy is associated with overexpression of MERTK, however further investigation is needed to discover the regulatory mutation for the better understanding of the disease pathogenesis." (PMID 25517981, 2014). "Among these pieQTLs, 27 are associated with retinopathies, including 3 that interact with their own eGene promoter (MYO7A, MERTK and PRPH2 genes)." (PMID 36207300, 2022). "This study adds further support for regulatory disruption of the MERTK gene in Swedish Vallhund retinopathy, although to establish this functional overexpression model more work is required to further investigate MERTK biology in retinal function." (PMID 28813472, 2017). "This condition does represent a form of PRA involving both the RPE and the photoreceptors, although its clinical presentation and the involvement of MERTK suggests that this retinopathy is primarily related to a defect in the RPE." (PMID 28813472, 2017). "Our study adds further support for regulatory disruption of MERTK in Swedish Vallhund retinopathy; however, further work is required to establish a functional overexpression model." (PMID 28813472, 2017). "Our study establishes a novel gain-of-function model for the MERTK biology and provides a therapy model for retinopathy MERTK inhibitors." (PMID 25517981, 2014). "We obtained retinal tissue samples from four retinopathy affected SVs and two control dogs and used them to quantitate transcript levels of the four retinal candidate genes, MERTK, NPHP1, ANAPC1 and KRCC1 in the critical region." (PMID 25517981, 2014). "Our study has independently replicated a previously published association with retinopathy and the MERTK locus in the Swedish Vallhund and has identified a LINE-1 repeat element insertion in intron 1 of the MERTK gene that shows a strong statistical association with retinopathy." (PMID 28813472, 2017). "sMer can bind to Gas6 and inhibit Gas6-mediated MERTK activation, which in turn could result in the impaired phagocytosis and retinopathy." (PMID 25517981, 2014). "However, while the causative variant remains to be found, positional and functional evidence support the role of MERTK in the SV retinopathy." (PMID 25517981, 2014). "Upon confirmation of the MERTK overexpression with subsequent downstream mechanisms, existing MERTK inhibitors may provide a therapeutic option for the retinopathy dogs." (PMID 25517981, 2014). "Indeed the establishment that it is intact MERTK that is being overexpressed in affected Vallhunds is important, as is whether this occurs before the development of disease and that it is therefore a cause and not a consequence of retinopathy." (PMID 28813472, 2017).
cardiovascular disease (5 papers, 2019 to 2025). "To further reveal the key role of MerTK in cardiovascular diseases, we performed the second big data analytics focusing on aortic tissues of human cardiovascular diseases based on RNA-seq data from IPA database with a total of 427 samples." (PMID 40953531, 2025). "Our data showed that, compared to normal control group, MerTK is higher expressed in embryotic aorta while it is significantly inhibited in cardiovascular diseases, particularly respiratory tract disease (RTD)-related cardiovascular diseases." (PMID 40953531, 2025). "This big data analytics provides the rationale for a novel study area in the role of endothelial MerTK in RTD-related cardiovascular diseases that needs to be further investigated." (PMID 40953531, 2025). "In the cardiovascular system, MerTK is highly expressed in cardiovascular cells (e.g., ECs, SMCs, and macrophages) and cardiovascular tissues (e.g., plaque, blood vessel and heart), indicating the potential role of MerTK in cardiovascular diseases." (PMID 38341954, 2024). "However, MerTK may undergo cleavage resulting in defective efferocytosis in cardiovascular diseases, brain disorders, and other diseases, making MerTK restoration a promising therapeutic strategy to treat these disease conditions." (PMID 38341954, 2024).
neurodegenerative disease (4 papers, 2021 to 2025). A disorder of the central nervous system characterized by gradual and progressive loss of neural tissue and neurologic function. "In microglia, MERTK signalling regulates the balance between pro‐inflammatory and anti‐inflammatory responses, a key mechanism in MS and other neurodegenerative diseases." (PMID 41239018, 2025). "Overall, the emerging evidence suggests that dysregulation of MERTK and AXL is a feature broadly shared by neurodegenerative disease and neuroinflammation." (PMID 40596721, 2025).
brain disorder (2 papers, 2024). A disease affecting the brain or part of the brain. "In brain, MerTK is mainly expressed in microglia, infiltrated macrophages and astrocytes, and its expression increases in brain disorders such as traumatic brain injury (TBI), stroke and brain tumors." (PMID 38341954, 2024).
hematologic malignancies (2 papers, 2016 to 2017). "Targeted inhibition of members of the TAM (TYRO-3, AXL, MERTK) family of receptor tyrosine kinases has recently been investigated as a novel strategy for treatment of hematologic malignancies." (PMID 27834816, 2016). "In summary, targeted inhibition of members of the TAM (TYRO-3, AXL, MERTK) family of receptor tyrosine kinases has recently been investigated as a novel strategy for treatment of hematologic malignancies." (PMID 27834816, 2016). "MERTK and AXL are both members of the TAM family receptor tyrosine kinases and MERTK has been validated as a target in AML and other hematologic malignancies." (PMID 29806049, 2017).
metabolic disease (1 paper, 2019). A congenital disorder (due to inherited enzyme abnormality) or acquired (due to failure of a metabolically important organ) disorder resulting from an abnormal metabolic process. "Recent lines of evidence highlight the involvement of myeloid-epithelial-reproductive tyrosine kinase (MerTK) in metabolic disease associated with liver damage." (PMID 31191323, 2019).
neurological disease (1 paper, 2020). "We investigated the levels and localization of the macrophage markers Iba1 and MER Proto-Oncogene, Tyrosine Kinase (MERTK) in ALS-CP and non-neurological disease controls." (PMID 32586411, 2020).
MERTK also shares sentences with these, for which no sentence is quoted: idiopathic pulmonary fibrosis (5 papers); chronic hepatitis C (3); Leber congenital amaurosis (3); metastatic melanoma (3); adenoma (2); aneurysm (2); Hypertension (2); inflammation (2); Stargardt disease (2); Usher syndrome (2); uveal melanoma (2); acute lung injury (1); acute myocardial infarction (1); acute-on-chronic liver failure (1); adrenoleukodystrophy (1); AIDS (1); alcohol dependence (1); allergic asthma (1); allergic rhinitis (1); amyloid (1); angiosarcoma (1); aortic valve stenosis (1); Arrhythmia (1); Ascites (1); astrocytic tumor (1); atrial fibrillation (1); autoimmune myocarditis (1); bacterial infections (1); benign familial hematuria (1); bestrophinopathies (1).
A further 84 diseases each share a sentence with MERTK in 1 paper.